CTLA4 (cytotoxic T-lymphocyte associated protein 4)
Diseases named in the same sentence as CTLA4 in open-access papers (continued):
Sharing a sentence is not in itself a finding about the gene and the disease.
conjunctival melanoma (2 papers, 2020 to 2022). "However, case reports showing responses to immune checkpoint inhibition, including responses to anti-CTLA4 monotherapy, anti-PD1 monotherapy, and combined anti-PD1/anti-CTLA4 therapy, support this treatment option in conjunctival melanoma." (PMID 32718045, 2020).
cranial neuropathies (2 papers, 2024 to 2025). "Conversely, peripheral neuropathy has been associated with CTLA-4 inhibitor therapy (either alone or in conjunction with PDL-1 inhibitors), and cranial neuropathy to CTLA-4 and PDL-1 inhibitors." (PMID 39199458, 2024).
craniopharyngioma (2 papers, 2019 to 2023). A benign, partly cystic, epithelial tumor of the sellar region, presumably derived from Rathke pouch epithelium. "The unique immune signature observed in craniopharyngiomas, characterized by an increase in epithelial–mesenchymal transition, CTLA-4, and PD-1 expression, suggests the potential for targeting these immune checkpoints." (PMID 37509316, 2023). "The third group, consisting mostly of craniopharyngiomas, was characterized by an increase in EMT, CTLA-4, and PD-1 expression." (PMID 37509316, 2023).
cutaneous leishmaniasis (2 papers, 2018 to 2020). Leishmaniasis affecting the skin. "Consequently, the expression of PD-1, CTLA-4, 2B4, CD160, and TIM-3 was evaluated ex vivo in PBMCs from 10 HD, 4 asymptomatic subjects, 5 patients cured of cutaneous leishmaniasis and 4 patients with active CL." (PMID 30510917, 2018).
demyelination (2 papers, 2021). "In a model of EAE with anti-CTLA4 monoclonal antibody treated mice, disease severity was also exacerbated, indicating that CTLA4 pathway also plays a role attenuating T-cell activation in immune-mediated CNS demyelination." (PMID 33897597, 2021).
DiGeorge syndrome (2 papers, 2021 to 2025). "DiGeorge syndrome (del22q11) was most common, followed by mutations in CTLA4, RMRP, IKZF1, and KMT2D." (PMID 33968040, 2021).
diphtheria (2 papers, 2012 to 2013). A Gram-positive bacterial infection caused by Corynebacterium diphtheriae. "Conversely, few IFN-γ-producing T cells responsive to tetanus and diphtheria toxoids expressed CTLA-4 and LIR-1." (PMID 22574131, 2012). "A low co-expression between CTLA-4 and LIR-1 was observed on CD4+ IFN-γ+ T cells in response either to the parasite lysate (median percentage ± SD = 10±11, range = 2.1–37) or to diphtheria toxoids (median percentage ± SD = 2.9±5.4, range = 0.7–12)." (PMID 22574131, 2012).
dry mouth (2 papers, 2021 to 2025). "Xerostomia (dry mouth) is a common manifestation, with an incidence of 0.3% in patients receiving anti-PD-1/PD-L1 monotherapy and 2.5% in those on combination therapy with anti-CTLA-4 agents." (PMID 41221037, 2025).
E. coli infection (2 papers, 2024 to 2025). "Protein network analysis indicated that genes such as FOS, CTLA4, APOA1, CEL, FRK, and AGTR1 had the strongest association with other genes, highlighting their crucial roles in E. coli infection." (PMID 39707535, 2024).
epididymal-orchitis (2 papers, 2021 to 2024). "Notably, two case reports documented incidences of orchitis and epididymal-orchitis in individuals undergoing treatment with anti-PD1/anti-CTLA4 and anti-PD1 agents, respectively." (PMID 39040288, 2024). "Two case reports described a case of orchitis and epididymal-orchitis during treatment with anti-PD1/anti-CTLA4 and anti-PD1, respectively." (PMID 34597942, 2021).
esophagitis (2 papers, 2021 to 2025). An acute or chronic inflammatory disease affecting the esophageal wall. "Retrospective evidence supports this trend: in a study of 21 patients with ICI-induced oesophagitis, 15 (71%) received anti-PD-1/PD-L1 monotherapy, 1 (5%) received anti-CTLA-4 monotherapy alone, and 5 (24%) received combination therapy." (PMID 41221037, 2025).
focal segmental glomerulosclerosis (2 papers, 2019 to 2020). A renal disorder characterized by sclerotic lesions in the glomeruli. "On the other hand, the +49GG genotype, associated with decreased expression of CTLA-4, increases the risk of MCD, focal segmental glomerulosclerosis, and membranous nephropathy." (PMID 31177287, 2019).
gastrointestinal stromal tumor (2 papers, 2018 to 2019). "In a mouse model of gastrointestinal stromal tumor (GIST), imatinib (a broad-spectrum TKI) was combined with an anti-CTLA-4 mAb to block T-cell immunosuppression mediated by indoleamine 2,3-dioxygenase (IDO)." (PMID 30191140, 2018).
germinoma (2 papers, 2019 to 2025). A malignant germ cell tumor arising in the central nervous system. "Reports have indicated that monotherapy with PD-1 monoclonal antibodies in germinoma patients, as well as combination therapy with PD-1 and CTLA-4 monoclonal antibodies in CNS NGGCT patients, both demonstrated some therapeutic efficacy." (PMID 39958339, 2025). "Regarding immune checkpoints, our study revealed that CTLA-4 was positively expressed in over 60% of germinoma cases and more than 40% of NGGCT cases." (PMID 39958339, 2025). "However, the positive expression rates of CTLA-4 in germinoma, YST, and CC (33.33%, 41.18%, and 37.50%, respectively) were significantly higher than in MT." (PMID 39958339, 2025). "The expression of CTLA-4 may further amplify this effect, particularly in germinomas." (PMID 39958339, 2025). "In germinomas, CD3+ and Foxp3+ cells strongly correlated with CTLA-4 expression (p<0.001), and CD4+, CD8+, and Foxp3+ cells with PD-1 expression (p<0.05)." (PMID 39958339, 2025). "Additionally, CTLA-4 expression was detected in 58.06% of cases, while PD-1 and PD-L1 were expressed in over 90%, with higher CTLA-4 levels in germinomas and elevated PD-L1 levels in NGGCTs." (PMID 39958339, 2025).
granulomas hepatitis (2 papers, 2021 to 2022). "From a histological perspective, anti-CTLA-4 inhibitor causes granulomas hepatitis with central vein endotheliitis, while anti-PD-1/PD-L1 inhibitor induces a heterogenous injury pattern without granulomatous inflammation." (PMID 34046801, 2021). "In the context of anti-cytotoxic T-lymphocyte-associated protein-4 (anti-CTLA-4) treatment, but not anti-PD-1 monotherapy, hepatic granulomas may be seen." (PMID 35936135, 2022).
Hepatosplenomegaly (2 papers, 2019 to 2020). Simultaneous enlargement of the liver and spleen. "Hepatosplenomegaly, characterized by a simultaneous enlargement of the liver and the spleen, was significantly less pronounced in mice preventively, but not therapeutically, treated with CTLA-4-Ig compared to controls." (PMID 31950032, 2019).
histiocytic sarcoma (2 papers, 2016 to 2018). An aggressive malignant neoplasm with a poor response to therapy, usually presenting as stage III/IV disease. "It is unclear whether costimulatory molecules, including CD28, cytotoxic T-lymphocyte-associated antigen-4 (CTLA-4), and programmed death-1 (PD-1), are expressed on peripheral blood lymphocytes (PBLs) of canine patients with histiocytic sarcoma." (PMID 26901565, 2016). "The expression level of CTLA-4 on CD4+ lymphocytes was significantly higher in the histiocytic sarcoma group (mean ± standard deviation: 3.20% ± 1.74%) than in the control group (1.27% ± 0.79%; P = 0.048)." (PMID 26901565, 2016). "The expression of CTLA-4 on CD8+ lymphocytes was also significantly higher in the histiocytic sarcoma group (4.35% ± 1.37%) than in the other tumor group (1.32% ± 0.82%; P = 0.003) and the control group (0.62% ± 0.68%; P = 0.003)." (PMID 26901565, 2016). "The objective of this study was to evaluate the expression of CD28, CTLA-4, and PD-1 molecules on PBLs of patients with histiocytic sarcoma, patients with other tumors, and healthy controls." (PMID 26901565, 2016). "The expression of CTLA-4 on CD8+ lymphocytes was significantly higher in the histiocytic sarcoma group than in the other two groups." (PMID 26901565, 2016). "The expression level of CTLA-4 on CD4+ lymphocytes was significantly higher in the histiocytic sarcoma group than in the control group." (PMID 26901565, 2016). "Overexpressions of CTLA-4 and PD-1 suggested suppression of antitumor immunity in dogs with histiocytic sarcoma; these molecules may represent new therapeutic targets for the treatment of canine histiocytic sarcoma." (PMID 26901565, 2016). "In contrast, the presence of CD8+ lymphocytes, the main tumor killers in specific immunity, showing overexpression of CTLA-4 indicated that antitumor immunity may be suppressed in dogs with histiocytic sarcoma." (PMID 26901565, 2016). "In particular, CTLA-4 may play an important role in antitumor activity in canine histiocytic sarcoma because of the high expression of the ligand CD86, which can bind to CTLA-4." (PMID 26901565, 2016). "A CTLA-4 blockade may induce restoration of antitumor immunity against histiocytic sarcoma." (PMID 26901565, 2016). "CTLA-4 expression was significantly increased on CD4+ and CD8+ lymphocytes in the histiocytic sarcoma group." (PMID 26901565, 2016). "The present results provided evidence showing that the expression levels of CTLA-4 on both CD4+ and CD8+ lymphocytes and PD-1 on CD8+ lymphocytes in peripheral blood obtained from dogs with histiocytic sarcoma were upregulated." (PMID 26901565, 2016). "In conclusion, the present study demonstrated upregulation of CTLA-4 expression on both CD4+ and CD8+ T cells and PD-1 expression on CD8+ T cells in peripheral blood obtained from dogs with histiocytic sarcoma." (PMID 26901565, 2016). "Therefore, the expression of CTLA-4 on peripheral lymphocytes may not be influenced by the tumor type of the histiocytic sarcoma." (PMID 26901565, 2016). "CD28, CTLA-4, and PD-1 expression levels were also compared between four dogs with localized histiocytic sarcoma and four dogs with disseminated histiocytic sarcoma in the histiocytic sarcoma group and five dogs with metastasis and five dogs without metastasis in the other tumor group." (PMID 26901565, 2016).
infectious encephalitis (2 papers, 2019 to 2024). An acute infectious process that affects the brain tissue. "Non-infectious encephalitis/myelitis was reported more with anti-PD-1/PD-L1 than with anti-CTLA-4 (ROR 2.5, 95% CI 1.6–3.9) and with combination therapy compared with monotherapy (ROR 2.0, 95% CI 1.4–2.7)." (PMID 31118078, 2019).
inflammatory skin disease (2 papers, 2022 to 2024). Inflammatory skin disorders covers a broad category that includes many conditions ranging in severity, from mild itching to grave medical health complications These disorders are common in people of all ages and races. "Notably, we found an increased percentage of Tregs (FOXP3, CTLA4) in LP skin (P = 0.02), similar to other inflammatory skin diseases." (PMID 39190494, 2024).
invasive ductal carcinomas (2 papers, 2018 to 2025). "Subcategorically, CTLA-4 was positive in 3 of 8 (37.5%) ductal carcinoma in situ, 40 of 73 (55%) of invasive ductal carcinomas, 4 of 10 (40%) of invasive lobular carcinomas and 2 of 2 (100%) of invasive tubular carcinomas." (PMID 29672601, 2018). "Group II, summary of the breast invasive ductal carcinomas showing the CTLA-4 staining reactions, scores, interpretations, and percentages of stained lymphocytes." (PMID 29672601, 2018).
kidney damage (2 papers, 2021 to 2025). "In contrast, less severe morphological alterations were detected in animals in groups C and E, suggesting that treatment with CTLA-4-Ig with or without microbubble exposure were associated with reduced pathological kidney damage in this DN model system." (PMID 33714204, 2021). "In many cases, this could be a successful therapeutic strategy, which would allow two families of ICIs to be included in the therapy without increasing the risk of suffering adverse renal effects (the incidence of kidney damage is not greater than after a single anti-CTLA-4)." (PMID 40149687, 2025).
localized scleroderma (2 papers, 2024 to 2025). Localized scleroderma is the skin localized form of scleroderma characterized by fibrosis of the skin causing cutaneous plaques or strips. "There are also rare cases of morphea linked to chemotherapy and immunotherapy treatments, including PD-1 and CTLA-4 inhibitors." (PMID 39259320, 2024).
lymphedema (2 papers, 2009 to 2024). Excess fluid collection in tissues, causing swelling. "To elucidate the transcriptomic features and pathways underlying the protective/therapeutic effect of anti-CTLA4 in lymphedema, we performed bulk RNA sequencing analyses of full-thickness tail skin from anti-CTLA4 treated and control mice." (PMID 39737964, 2024). "Examining the different immunotherapy treatments present in our patient cohort, we were able to attribute the lymphedema protective effect to the anti-CTLA4 monotherapy, which reduced lymphedema risk to the level of the lymph node biopsy risk group." (PMID 39737964, 2024). "In agreement with the preclinical results obtained, anti-CTLA4 therapy downregulated all key processes linked to lymphedema, namely fibrosis, epithelium degeneration and edema, further strengthening the therapeutic effect of the examined agent." (PMID 39737964, 2024). "The results indicate that the patients receiving lymphadenectomy followed by anti-CTLA4 therapy have a significantly reduced risk of developing lymphedema compared to untreated patients or patients receiving a different immune checkpoint inhibitor scheme." (PMID 39737964, 2024). "While the prevalence under anti-PD1 therapy was comparable to the prevalence observed in patients without treatment (19% anti-PD1 treatment vs. 18.8% only LAD/untreated), the anti-CTLA4 treatment showed a remarkable and significant reduction of lymphedema risk." (PMID 39737964, 2024). "While the anti-CTLA4-mediated expansion of the Tregs offers a solid explanation of the protective function of the intervention against lymphedema, the underlying molecular players remain unclear, as our understanding of the immune checkpoint inhibitors is still incomplete." (PMID 39737964, 2024). "The results from the retrospective patient cohort analysis indicated that CTLA4 is a potential target molecule in lymphedema pathophysiology." (PMID 39737964, 2024). "Based on the well-established concept that immunomodulation influences lymphedema onset and development, we evaluate in this study the repurposing of the immune checkpoint inhibitor anti-CTLA4 in lymphedema treatment." (PMID 39737964, 2024). "Our data thus show that anti-CTLA4 with its lymphedema-protective and anti-tumor properties is a promising candidate for more diverse application in the clinics." (PMID 39737964, 2024). "Anti-CTLA4 treatment was effective in the experimental model, leading to significantly decreased lymphedema and improved lymphatic function." (PMID 39737964, 2024). "The successful results cemented the efficacy of the intervention and suggested that lymphedema improvement is mediated through an anti-CTLA4-dependent Treg expansion both locally and systemically." (PMID 39737964, 2024). "Inspired by the encouraging results of the retrospective patient cohort analysis as well as the increased presence of CTLA4+ cells in lymphedema patients, we investigated the anti-CTLA4 treatment in the well-established murine-tail lymphedema model." (PMID 39737964, 2024). "In order to dissect the effect of immunotherapy on lymphedema risk, we analyzed within the LAD group if immunotherapy either as monotherapy or in combination (anti-CTLA4, anti-PD1 or interferon) influences lymphedema risk." (PMID 39737964, 2024). "Only 2.9% of the patients receiving anti-CTLA4 treatment post-LAD developed lymphedema, indicating a highly significant effect of anti-CTLA4 monotherapy in preventing lymphedema." (PMID 39737964, 2024). "We further confirm the clinical results in a mouse-tail lymphedema model, where anti-CTLA4 administration significantly reduces edema formation and improves lymphatic function." (PMID 39737964, 2024). "Gene Set Enrichment Analysis of the differentially expressed genes revealed downregulated keratinization and keratinocyte differentiation within the anti-CTLA4 treated tissue, a finding consistent with improved lymphedema outcome." (PMID 39737964, 2024).
lymphedema (continued). "In contrast, expression of Foxp3, GITR, TGFβ, and CTLA-4, known to be expressed by regulatory T cells, was significantly impaired in patients with lymphedema." (PMID 19381284, 2009). "As CTLA4 administration was found to have a protective function both in prospective preclinical and retrospective human studies, we next sought to assess in depth the changes induced in the local and systemic cytokine milieu upon the anti-CTLA4 treatment in the lymphedema mouse tail model." (PMID 39737964, 2024). "It is important to highlight that the effect of anti-CTLA4 treatment has been investigated in depth in the context of tumor immunology, remaining unclear how precisely these findings can be transferable to the lymphedema model." (PMID 39737964, 2024). "Importantly, consistent with previous reports and the experimental models, we could demonstrate the increased FOXP3+ and CTLA4+ cell infiltration in human lymphedema biopsies and the increased CTLA4 expression in the subcutaneous tissue of secondary lymphedema patients." (PMID 39737964, 2024). "To determine the role of nTregs in the development of lymphedema, we stimulated PBMCs from CP and INF patients with BmA or PPD for 24 h and examined the mRNA expression of nTreg markers—Foxp3, GITR, TGFβ, and CTLA-4—by real-time RT-PCR." (PMID 19381284, 2009). "Our results show that while Foxp3, GITR, TGFβ, and CTLA-4 are significantly upregulated in patients with asymptomatic infection, there is a significant lack of upregulation in filarial lymphedema patients." (PMID 19381284, 2009). "Interestingly, the combination therapy of anti-CTLA4 and anti-PD1 tended to reduce lymphedema risk without reaching significance." (PMID 39737964, 2024).
Lynch syndrome (2 papers, 2023 to 2025). An autosomal dominant hereditary neoplastic syndrome characterized by the development of colorectal carcinoma and a high risk of developing endometrial carcinoma, gastric carcinoma, ovarian carcinoma, renal pelvis carcinoma, and small intestinal carcinoma. "Despite the limitations of a single case report mentioned here, the rapid and ongoing therapy response in overcoming the acquired PD-1 resistance by adding an anti-CTLA-4 antibody may be a promising strategy for other patients with Lynch syndrome-associated CRC." (PMID 37569431, 2023). "It should be noticed that CTLA-4 antibody may not be necessary for patients with Lynch syndrome." (PMID 40818457, 2025).
maculopapular rash (2 papers, 2023 to 2024). "Notably, PD-1/PD-L1 antibodies are of lower risk of maculopapular rashes (MPR) compared to CTLA-4 antibodies." (PMID 39494351, 2024). "The number of maculopapular rash cases accounted for the largest proportion in our study, which represented the most common cutaneous irAEs observed with PD-1/PD-L1- and CTLA-4-related regimens." (PMID 37332342, 2023).
memory impairment (2 papers, 2015 to 2025). "Patients who develop anti-CTLA-4 associated endocrinopathies may present with nonspecific symptoms such as fatigue, weakness, headache, nausea, behavioral changes, visual impairments, memory loss, decreased libido, anorexia, insomnia, and cold or heat intolerance." (PMID 25694832, 2015).
minimal change disease (2 papers, 2018 to 2020). "A further mechanism leading to podocyte foot process impairment, as observed for minimal-change disease and focal segmental glomerulosclerosis, could be the persistent, chronic release of inflammatory cytokines by T cells associated to ICIs-induced abrogation of CTLA-4 signaling." (PMID 33162990, 2020).